FST (follistatin)
Diseases named in the same sentence as FST in open-access papers (continued):
Sharing a sentence is not in itself a finding about the gene and the disease.
ovarian carcinoma (7 papers, 2012 to 2025). A malignant neoplasm originating from the surface ovarian epithelium. "One plausible mechanism by which FST may exert its resistance-promoting effects is by creating an immune-cold TME, as suggested by the negative enrichment of genes associated with inflammatory responses in ovarian cancer cells overexpressing FST." (PMID 38392348, 2024). "An analysis of intraperitoneal aspirates collected from chemotherapy-naïve ovarian cancer patients, both before and after undergoing cycles of treatment, indicated an immediate upregulation of FST levels following cisplatin treatment." (PMID 38392348, 2024). "This group showed that FST is upregulated in response to cisplatin treatment in epithelial ovarian cancer cells." (PMID 38392348, 2024). "The knock-down of FST significantly reduced the proliferation of the immortalized ovarian surface epithelial and human ovarian carcinoma cell line SKOV3." (PMID 34239543, 2021). "We performed two key functional assays namely cell proliferation assay and cell migration assay using SKOV3 cells as well as IOSE cells to demonstrate a potential role of FST in ovarian cancer development." (PMID 22685544, 2012). "Data obtained from this quantitative FST assay suggests that induction in cellular BRCA1 levels in turn stimulates extracellular FST secretion in human ovarian cancer cells." (PMID 22685544, 2012). "However, one study demonstrated higher serum follistatin levels in ovarian cancer patients compared to patients with benign ovarian cysts." (PMID 33671851, 2021). "In this study, we used immortalized ovarian surface epithelium (IOSE) cells from normal human ovary (IOSE 7576 and IOSE 397) and from an ovarian cancer patient with BRCA1 mutation, IOSE 592F, to investigate the role of BRCA1 in mediating FST secretion in these cells." (PMID 22685544, 2012). "Thus, a possible role of FST as an Activin antagonist in the pathogenesis of ovarian cancer requires further investigation." (PMID 22685544, 2012). "FST binds to Activin in an antagonistic manner and elevated expression of cellular FST may leads to cytoprotection role in ovarian cancer patients." (PMID 22685544, 2012). "Elevated follistatin expression in tumors was associated with worse overall survival in CCNE1-amplified HGSOC, and its presence in blood may serve as an early diagnostic marker for ovarian cancer." (PMID 41029436, 2025). "Interestingly, FST drives resistance to immune checkpoint inhibitors in ovarian cancer cells, but future research is needed to determine whether similar mechanisms are at play in HNSCC." (PMID 37492374, 2023). "Finally, additional studies specifically examining the interplay between BRCA1 and FST and its effect(s) on cellular processes may be helpful in devising targeted treatment for human ovarian cancer." (PMID 22685544, 2012). "We measured levels of follistatin (FST) and follistatin-like 3 (FSTL3) in 96 ovarian cancer patient ascites samples and found that FSTL3 overexpression was more predominant than FST and associated with poorer survival outcomes." (PMID 41029436, 2025). "In this study, we identified significant overexpression of both FST and FSTL3 in 96 ascites samples from ovarian cancer patients." (PMID 41029436, 2025). "To evaluate the relative expression of FST and FSTL3 in ovarian cancer, we measured the concentrations of these proteins by ELISA in 96 ascites samples from 77 patients with various peritoneal tumors of ovarian cancer and other origins, both chemo-naïve and treated." (PMID 41029436, 2025). "Transcriptomic studies have shown that cisplatin treatment upregulates FST within the cancer stem cell population of HNSCC, suggesting that comparable resistance mechanisms may be at play, as in ovarian cancer." (PMID 38392348, 2024).
ovarian carcinoma (continued). "BRCA1 may induce its cytoprotective effect via modulating the expression of both SMAD6 and FST, and in turn, may induce BMP signaling pathways, which may then inhibit or delay the progression of ovarian cancer, specifically epithelial-origin ovarian cancer." (PMID 22685544, 2012).
chronic kidney disease (6 papers, 2018 to 2025). Impairment of the renal function secondary to chronic kidney damage persisting for three or more months. "Increased follistatin levels occur also in inflammatory diseases and have been suggested to counteract catabolism in chronic kidney disease." (PMID 30165829, 2018). "However, under pathological conditions, particularly in elderly populations and patients with chronic kidney disease (CKD), high levels of follistatin can act negatively, being associated with inflammation and muscle wasting, increasing the risk of heart failure and mortality." (PMID 40943156, 2025). "In humans, urinary NGAL increased not only in AKI, but also in chronic kidney disease (CKD), and is a marker for delayed graft function following kidney transplantation, suggesting that the potential of urinary follistatin as a tubular injury marker is not limited to AKI." (PMID 38534369, 2024). "However, a negative correlation between follistatin and gait speed was observed in older adults and patients with chronic kidney disease." (PMID 32927586, 2020). "Moreover, the treatment with activin A-binding protein, follistatin, or with RAP-011, a ligand trap of ActRllA, has revealed an amelioration of renal fibrosis and chronic kidney disease-mineral bone disorder (CKD-MBD) findings in CKD models." (PMID 31236663, 2019).
endometriosis (6 papers, 2012 to 2024). The growth of functional endometrial tissue in anatomic sites outside the uterine body. "The expression of FST was decreased in the endometriosis group after 2, 4, 6, and 8 days of EPC treatment." (PMID 38402336, 2024). "An impaired expression of OMA and endometrial cripto (activin receptor antagonist), and follistatin (activin-binding protein) indicates an impaired activin pathway in endometriosis." (PMID 34405378, 2022). "Taken together, the role of follistatin as particularly an inhibitor of activin A confers a beneficial effect of this adipokine on endometriosis." (PMID 36289764, 2022). "Combinations of activin A and follistatin as markers of endometriosis showed the highest effectiveness." (PMID 34201813, 2021). "CA 125, Ca 19.9, ICAM-1, and IL-6 together with follistatin and urocortin have proven to be the most reliable markers for endometriosis diagnosis." (PMID 23093966, 2012). "Follistatin expression is abnormal in endometrioma and eutopic endometria of women with endometriosis, implying that failure of this pathway may contribute to endometriosis-related infertility." (PMID 35780124, 2022). "Thus, current experimental data suggest that a dysregulation of activin A and follistatin, a natural inhibitor of activin A bioactivity, may contribute to endometriosis." (PMID 36289764, 2022). "The greatest increase in the plasma follistatin level was observed in the ovarian and peritoneal forms in patients with deep infiltrating endometriosis (DIE) as well as in healthy controls, which excludes its use as a marker of endometriosis." (PMID 34201813, 2021).
heart failure (6 papers, 2012 to 2025). Inability of the heart to pump blood at an adequate rate to meet tissue metabolic requirements. "Follistatin is downregulated in the left ventricle of the heart after myocardial infarction, a reduction that is associated with myocardial fibrosis and heart failure following myocardial infarction." (PMID 41198895, 2025). "This study illustrated that the activin A–follistatin system was involved in endoplasmic reticulum stress (ERS)-mediated myocardial cell apoptosis in heart failure (HF)." (PMID 28208629, 2017). "We implemented a proof-of-concept study in heart failure patients in which treatment with high flavanol cocoa for 3 months yielded improved modulators of SkM regeneration (MyoD) and growth (follistatin), as did indicators of sarcomeric microstructural integrity." (PMID 34750405, 2021). "The insignificant change of myostatin in our heart failure patient may be attributed to the confounding effect of follistatin of which may antagonize myostatin during muscle mass regulation." (PMID 22957004, 2012). "Cardiac cachexia-related biomarkers including adiponection, follistatin and myostatin had been investigated in muscle, fat, and bone metabolism in heart failure metabolism, however, the relationship between circulating biomarkers and bone mineral density (BMD) in chronic HF remained unclear." (PMID 22957004, 2012). "Given the significant difference in the mean time since ACS in groups K and S (22 vs. 4 weeks), the elevated level of follistatin in group K may reflect the temporally delayed initiation of remodeling mechanisms that protect against the development of heart failure." (PMID 41198895, 2025). "This study thus aimed to explore the effects of the activin A–follistatin system on myocardial cell apoptosis in heart failure (HF) rats in order to determine whether or not the mechanism operates through the endoplasmic reticulum stress (ERS) pathway." (PMID 28208629, 2017).
Infertility (6 papers, 2014 to 2023). "Mice with uterine FST knockdown have severe infertility caused by failure to decidualize to support an embryo implantation." (PMID 36497076, 2022). "Furthermore, detailed mechanistic and functional studies are necessary to understand the exact role of the activins and their functional antagonists, inhibin and follistatin, in this process leading to severe inflammation causing infertility." (PMID 28205525, 2017). "Transgenic female mice with gain-of-function FST, in which mouse follistatin was over-expressed, developed thin uteri and small ovaries, resulting in infertility." (PMID 24669966, 2014). "The increased expression of ActRIIa, ActRIIb, and follistatin in the endometrium of these patients may contribute to their infertility due to adenomyosis." (PMID 35780124, 2022).
spinal muscular atrophy (6 papers, 2015 to 2024). A motor neuron disease that affect the muscles, and characterized by muscle weakness and atrophy resulting from progressive degeneration and irreversible loss of the anterior horn cells in the spinal cord (i.e., lower motor neurons) and the brain stem nuclei. "The follistatin:myostatin ratio was significantly increased in spinal muscular atrophy subjects and inversely correlated with motor severity." (PMID 38487549, 2024). "This study aimed to investigate the role of serum levels of myostatin and follistatin as biomarkers for spinal muscular atrophy, considering muscle atrophy secondary to denervation as the main clinical manifestation of the disease." (PMID 38487549, 2024). "The administration of follistatin exerts a relevant therapeutic effect on spinal muscular atrophy in an animal model." (PMID 35972944, 2022). "Skeletal muscle gene expression of myostatin decreased and of follistatin increased following lesional muscle denervation in mice, consistent with findings in the spinal muscular atrophy transgenic mice meta-analysis and in the iliopsoas muscle of five patients with spinal muscular atrophy type 1." (PMID 38487549, 2024). "Furthermore, delivery of recombinant follistatin, a natural antagonist of myostatin, in a mouse model of spinal muscular atrophy, has been shown to increase the number and size of ventral horn cells together with the gross motor function of mice." (PMID 29070788, 2017). "Furthermore, follistatin treatment improves mean survival in another spinal motor neuron degenerative disease, spinal muscular atrophy (SMA), probably by rescuing skeletal muscle." (PMID 26914813, 2016).
lung adenocarcinoma (5 papers, 2014 to 2020). A carcinoma that arises from the lung and is characterized by the presence of malignant glandular epithelial cells. "Activin A (ActA)/follistatin (FST) signaling has been shown to be deregulated in different tumor types including lung adenocarcinoma (LADC)." (PMID 26950277, 2016). "By assaying serum FST levels, we found that it was significantly higher in patients with lung adenocarcinoma and ovarian mucinous adenocarcinoma than that in healthy control group (P<0.01)." (PMID 25347573, 2014). "Lung adenocarcinoma cells secreted FST in a serum-dependent manner, which is consistent with the FST secretion of pituitary cells." (PMID 25347573, 2014). "To further investigate the biological role of FST, we analyzed the effect of FST on activin A-induced lung adenocarcinoma cell apoptosis." (PMID 25347573, 2014). "In order to further clarify the clinical significance of FST, the expression of FST protein in tissues of lung adenocarcinoma with different grades was analyzed by immunohistochemical staining." (PMID 25347573, 2014). "In contrast, the positive ratio of serum FST levels were related to disease stages and differentiation grades of lung adenocarcinoma and ovarian mucinous adenocarcinoma." (PMID 25347573, 2014). "The results showed that the expression of FST in lung adenocarcinoma was correlated with the differentiation of lung adenocarcinoma." (PMID 25347573, 2014). "The recent studies have reported that FST was aberrantly expressed in human lung adenocarcinoma cells, suggesting that FST might be a potential biomarker for diagnosis of lung adenocarcinoma." (PMID 30377409, 2018). "In the previous study, we have reported serum FST overexpression in lung adenocarcinoma." (PMID 30377409, 2018). "FST expressions in lung adenocarcinoma were examined by immunohistochemical staining, we found that lung adenocarcinoma could produce FST and there was positive correlation between the level of FST expression and the differential degree of lung adenocarcinoma." (PMID 25347573, 2014). "Furthermore, the immunocytochemical staining revealed that human lung adenocarcinoma cell line A549 also produced FST protein." (PMID 25347573, 2014). "The results showed FST immunoreactivity in the glandular duct-like tissues of lung adenocarcinoma." (PMID 25347573, 2014). "The data revealed that lung adenocarcinoma cells secreted FST in FCS-dependent and time-dependent manner, while cells from non-tumor lung tissues could not secrete FST." (PMID 25347573, 2014). "The expression of FST in lung adenocarcinoma was correlated with the differentiation, that is to say, its expression became more pronounced as the grade became worse, i.e. from well-differentiated to poorly-differentiated lung adenocarcinoma." (PMID 25347573, 2014). "In addition, the results of CCK8 assay and flow cytometry showed that using anti-FST monoclonal antibody to neutralize endogenous FST significantly augmented activin A-induced lung adenocarcinoma cells apoptosis." (PMID 25347573, 2014). "Using ELISA to detect serum FST, we also found that the positive ratio of serum FST levels in patients with lung adenocarcinoma was correlated with the differentiation grade of lung adenocarcinoma, which was similar to the results of immunohistochemical staining." (PMID 25347573, 2014). "While after using anti-FST monoclonal antibody to neutralize endogenous FST, 10 ng/ml activin A could significantly induced apoptosis of lung adenocarcinoma cells (P<0.01)." (PMID 25347573, 2014). "Our previous studies discovered that ovarian adenocarcinoma can secrete FST, but whether lung adenocarcinoma can secrete FST and FST function is still unclear." (PMID 25347573, 2014). "However, whether FST can serve as a biomarker for diagnosis in lung adenocarcinoma of humans remains unclear." (PMID 25347573, 2014).
lung adenocarcinoma (continued). "FST production was identified in the supernatant of cultured lung adenocarcinoma cells, but was almost not found in the supernatant of control cells derived from non-tumor lung tissues in 10% FCS-IMDM." (PMID 25347573, 2014). "Furthermore, the results showed that primary cultured lung adenocarcinoma cells could secrete FST, while cells derived from non-tumor lung tissues almost did not produce FST." (PMID 25347573, 2014).
basal cell carcinoma (4 papers, 2009 to 2023). A carcinoma involving the basal cells. "FST has been shown to be associated with Basal cell carcinomas." (PMID 19832977, 2009). "This group also reported a concomitant expression of FOLLISTATIN (FST) in the stromal cells of basal cell carcinomas." (PMID 22648066, 2013).
Becker muscular dystrophy (4 papers, 2021 to 2023). Becker muscular dystrophy (BMD) is a neuromuscular disease characterized by progressive muscle wasting and weakness due to degeneration of skeletal, smooth and cardiac muscle. "Furthermore, in a clinical trial involving patients with Becker muscular dystrophy treated with follistatin delivered by an adeno‐associated virus, increased muscle fibre size distribution with muscle hypertrophy was noted, and no adverse effects were apparent." (PMID 37897141, 2023). "Recently, an antagonist of activin signaling-related ligands, follistatin (FS), was used in a Becker muscular dystrophy (BMD) proof-of-principle clinical trial with encouraging results." (PMID 35330385, 2022).
breast tumors (4 papers, 2009 to 2021). "In order to establish if these activin binding proteins are involved in breast tumor progression, the present study evaluated follistatin and FLRG pattern of mRNA and protein expression in normal human breast tissue and in different breast proliferative diseases." (PMID 19740438, 2009). "Interestingly, some of the negative regulators of activin signaling pathway such as follistatin, β-glycan, IGSF1, and IGSF10 showed downregulation in breast tumors compared with normal samples." (PMID 28721365, 2015). "This may reflect a fall in the secretion of follistatin from ER-ve breast tumours that is not seen in ER + ve tumours." (PMID 25884855, 2015).
colon carcinoma (4 papers, 2016 to 2021). "The Smad4-intact SW480 and Smad4-null HT29 colon cancer cell lines were treated with activins and follistatin, and cell cycle was analysed by flow cytometry." (PMID 34867090, 2021). "Our results showed significantly higher concentrations of follistatin at the gene and protein levels that positively correlated with the progression of colon cancer in the used model." (PMID 27835986, 2016). "Additionally, the effects of activins and follistatin proteins related to cell cycle and expression of apoptosis markers were investigated in the Smad-4 intact SW480 and Smad-mutated HT29 colon cancer cells." (PMID 34867090, 2021). "However, co-treating colon cancer cell lines with diverse concentration ratio of the different mature activin proteins (A, B or AB) in the presence of follistatin (1:1, 2:1 and 1:2) are required to verify our suggestion." (PMID 34867090, 2021). "Butyrate has been shown to downregulate Wnt activity in CC531 rat colon carcinoma cells by reducing the expression of 4 Wnt target genes that are upregulated in CRC [CCND1, c-MYC, FOSL1, and follistatin (FST)], but it has also been shown to induce Wnt signaling leading to stimulated apoptosis." (PMID 28077379, 2017). "Currently there is no report in the literature regarding the role of follistatin in colon cancer." (PMID 27835986, 2016).
gastric cancer (4 papers, 2007 to 2023). A primary or metastatic malignant neoplasm involving the stomach. "The result suggests a limited role of Chordin, Follistatin, and Noggin in regulation of BMP signaling in gastric cancer." (PMID 29720137, 2018).
Hyperglycemia (4 papers, 2019 to 2023). An increased concentration of glucose in the blood. "Follistatin and activins may be involved in the regulation of insulin sensitivity and inflammation status (activin A protects against hyperglycemia, hyperinsulinemia, and inflammation)." (PMID 31467615, 2019).